FKBPL (FKBP prolyl isomerase like)
Description:
May be involved in response to X-ray. Regulates p21 protein stability by binding to Hsp90 and p21.
Synonyms: WISp39; DIR1; NG7
Tractability: Antibody: its Gene Ontology location is reachable by antibodies, with high confidence. PROTAC: ubiquitination databases record sites on it; its protein half-life has been measured.
Gene: Protein-coding gene on chromosome 6 (32,128,697 to 32,131,070, reverse strand). Ensembl gene ENSG00000204315.
Subcellular location (Human Protein Atlas): Nucleoplasm; Mitotic spindle
Pathways (Reactome):
Cell Cycle: The role of GTSE1 in G2/M progression after G2 checkpoint
Gene Ontology:
Molecular function: protein binding
Biological process: response to radiation
Cellular component: extracellular region; cytosol
Genetic constraint (gnomAD): Loss-of-function variants: 31 observed, 29.96 expected, observed/expected ratio (o/e) 1.03, 90% interval 0.78 to 1.4. The synonymous counts are far from expectation, so gnomAD's model fits this gene poorly and the ratio says little. Missense variants: 355 observed, 453.63 expected, observed/expected ratio (o/e) 0.78, 90% interval 0.72 to 0.85. Synonymous variants: 134 observed, 180.71 expected, observed/expected ratio (o/e) 0.74, 90% interval 0.64 to 0.86.
Homologues: Orthologues: chimpanzee FKBPL (99% identical), macaque FKBPL (96% identical), pig FKBPL (85% identical), guinea pig FKBPL (85% identical), dog FKBPL (84% identical), rabbit FKBPL (79% identical), rat Fkbpl (76% identical), mouse Fkbpl (73% identical), tropical clawed frog FKBPL (29% identical), zebrafish fkbpl (14% identical), Caenorhabditis elegans fkb-5 (7% identical), Caenorhabditis elegans fkb-4 (7% identical), and 2 more. Paralogues in human: FKBP8 (20% identical), FKBP4 (17% identical), FKBP5 (17% identical), FKBP6 (15% identical), FKBP15 (14% identical), FKBP10 (12% identical), FKBP9 (12% identical), TTC9 (11% identical), TTC9B (11% identical), TTC9C (9% identical), FKBP7 (8% identical), FKBP14 (7% identical), and 6 more.
Diseases named in the same sentence as FKBPL in open-access papers:
FKBPL is named in the same sentence as 41 diseases in open-access papers, as found by Europe PMC text mining. Sharing a sentence is not in itself a finding about the gene and the disease. The quoted sentences say what the papers report.
breast carcinoma (14 papers, 2013 to 2025). "High levels of FKBPL are associated with increased survival and improved response to endocrine therapy in breast cancer patients." (PMID 41048997, 2025). "FKBPL’s role as a negative regulator of tumor growth, metastasis, and angiogenesis is established in studies of breast cancer (BC), where FKBPL’s high expression has been associated with a better prognosis of BC." (PMID 36295491, 2022). "In ER+ breast cancer, we have shown that FKBPL is in a HSP90-associated chaperone complex with ERα receptor and that it can regulate ER signalling." (PMID 30975104, 2019). "In addition to this, we have shown that high FKBPL levels are associated with a positive prognosis in breast cancer." (PMID 30975104, 2019). "It was reported that FKBPL overexpression decreases proliferation and clonogenicity of breast cancer cells via stabilizing newly synthesized p21." (PMID 38164287, 2024). "Ectopic expression of FKBPL inhibits the proliferation of breast cancer cells by stabilizing the cyclin-dependent kinase (CDK) inhibitor, p21." (PMID 38164287, 2024). "ALM201, like other FKBPL derivatives, inhibits breast cancer metastasis through Notch signalling, showing excellent safety profile in Phase 1 clinical trials, when applied for the treatment of ovarian cancer and solid tumor." (PMID 34195230, 2021). "FKBPL knockdown in breast cancer cells upregulated the stemness markers NANOG, OCT4, and SOX2 and increased the CSC fraction." (PMID 32268506, 2020). "Here, we expand on the role of FKBPL in ER+ breast cancer by investigating the effect of stable FKBPL overexpression in MCF-7 cells (D2) on CSC-like colonies, holoclones." (PMID 30975104, 2019). "Intracellular FKBPL regulates ER signalling and, as such, has prognostic value in terms of breast cancer survival." (PMID 30975104, 2019). "In this cohort of 3277 patients, FKBPL was a significant and independent predictor of breast cancer specific survival (BCSS), with low FKBPL expression being associated with shorter BCSS (HR = 1.31, 95% CI 1.15–1.50, p < 0.001)." (PMID 30975104, 2019). "Here, we evaluated FKBPL's prognostic ability in primary breast cancer tissue, represented on tissue microarrays (TMA) from 3277 women recruited into five independent retrospective studies, using immunohistochemistry (IHC)." (PMID 25906750, 2015). "In breast cancer cells, over-expression of FKBPL resulted in reduced cell proliferation, due to stabilization of newly synthesised cyclin-dependent kinase inhibitor, p21." (PMID 25906750, 2015). "In a meta-analysis, FKBPL levels were a significant predictor of BCSS; low FKBPL levels indicated poorer breast cancer specific survival (BCSS) (hazard ratio (HR) = 1.30, 95% confidence interval (CI) 1.14–1.49, p < 0.001)." (PMID 25906750, 2015). "Its regulation of estrogen signalling supported a role for FKBPL as a prognostic and/or predictive biomarker of response to endocrine therapy in breast cancer patients." (PMID 23457460, 2013). "Previous study demonstrated that FKBPL inhibited proliferation of breast cancer and lymphoma cells." (PMID 38164287, 2024). "Additionally, the treatment with an FK506-binding protein-like (FKBPL)-based peptide repressed a subpopulation of endocrine therapy-resistant CSC in ER+ breast cancer by interfering with DLL4 and Notch4 signaling." (PMID 34680255, 2021). "Similarly, RBCK1, an E3 ubiquitin-protein ligase, which regulates FKBPL levels, also demonstrated a potential role as a prognostic and predictive biomarker of response to endocrine therapy in breast cancer patients in terms of BCSS." (PMID 30975104, 2019). "Likewise, in a cohort of 2365 ER+ breast cancer patients, low FKBPL expression had also a significantly shorter BCSS compared to high FKBPL expression (HR = 1.34, 95% CI 1.13–1.58, p < 0.001)." (PMID 30975104, 2019). "In addition, FKBPL overexpression renders breast cancer cells more sensitive to tamoxifen." (PMID 38164287, 2024).
breast carcinoma (continued). "Therefore, since FKBPL and its peptides have demonstrated inhibitory effects on angiogenesis, CSC signalling and ER signalling, we hypothesised that FKBPL could also inhibit metastasis and endocrine therapy resistance driven by CSCs in breast cancer." (PMID 30975104, 2019). "Furthermore, these data provide support for the use of the FKBPL biomarker as a prognostic aid to patient management in early-stage ER+, LN-, Her2- breast cancer, which could be easily and cheaply incorporated alongside these standard biomarkers." (PMID 25906750, 2015). "FKBPL and its peptide derivative, ALM201, are shown to decrease the migration and invasion of breast cancer stem cells (CSC) and inhibit the growth of mammospheres of endocrine therapy-resistant breast CSC." (PMID 36295491, 2022). "In ER+ breast cancer, using MCF-7 cells and ER+ breast cancer samples, we also demonstrated FKBPL-mediated CSC differentiation, inhibition of CSCs resistant to endocrine therapy and delay in tumour initiation." (PMID 30975104, 2019). "The identified shRNAs target genes involved in signaling pathways known to regulate breast cancer stem cells, including WNT (SFRP1), CD44 (FKBPL), and the PI3K/AKT (FOXO3A) signaling pathways." (PMID 26595803, 2016). "FKBPL itself, the endogenous protein from which ALM201 was derived, has been proposed as a biomarker for response in breast cancer, suggesting that certain functional aspects of FKBPL may provide an overall survival benefit to certain patients." (PMID 35568736, 2022). "In order to demonstrate that FKBPL-based clinical peptide, ALM201, is able to target endocrine therapy resistant CSCs in ER+ breast cancer, we treated the ER+ breast cancer cell line, MCF-7, with estradiol (100 nM) ± tamoxifen (1 μM) ± ALM201 (1 nM) and carried out mammosphere assay." (PMID 30975104, 2019). "Since CSCs are known to be associated with invasion and metastasis, here we addressed whether the FKBPL-peptide could inhibit invasion in vitro and whether this could be translated in an experimental model of metastasis using the triple negative metastatic MDA-MB-231 breast cancer cells." (PMID 30975104, 2019).
preeclampsia (12 papers, 2021 to 2025). Preeclampsia is a hypertensive disorder of pregnancy that is characterized by new-onset hypertension with proteinuria presenting after 20 weeks of gestation, and depending on mild or severe forms may initially present with severe headache, visual disturbances, and hyperreflexia. "Placental health relies on a tightly regulated angiogenic balance, with FKBPL being implicated as an important mechanism in placental dysfunction and preeclampsia pathogenesis." (PMID 41285723, 2025). "FKBPL has emerged as a new predictive and diagnostic biomarker and a therapeutic target of preeclampsia." (PMID 40109359, 2025). "The model included HUVECs and a first trimester trophoblast cell line (ACH-3P) to investigate the signaling and mechanisms of FKBPL and Gal-3, which are inflammatory proteins implicated in preeclampsia." (PMID 41050941, 2024). "Two emerging pathways, anti-angiogenic FK506-binding protein-like (FKBPL) and pro-inflammatory galectin-3 (Gal-3), have been implicated in preeclampsia and associated cardiovascular complications." (PMID 36652019, 2023). "Given that FKBPL has anti-angiogenic properties, increased levels of FKBPL are associated with restricted angiogenesis, which is a hallmark of preeclampsia." (PMID 36652019, 2023). "This is the first study that explores the cardiovascular health in the RUPP model of preeclampsia and the association of FKBPL in cardiac dysfunction in preeclampsia." (PMID 33879252, 2021). "Using this cut-off point, a univariate logistic regression model demonstrated, that women with a CD44/FKBPL ratio above 143.6 or 155.1 had a 2.5- or 2.4-fold increased risk of developing preeclampsia later in pregnancy (P = 0.02, P = 0.03), respectively." (PMID 32617576, 2021). "At 20 weeks of gestation, a high plasma CD44/FKBPL ratio was independently associated with the 2.3-fold increased risk of preeclampsia (odds ratio = 2.3, 95% confidence interval [CI] 1.03-5.23, P = 0.04)." (PMID 32617576, 2021). "Disclosure Summary: LM and TR are listed as inventors on the FKBPL patent (“Assay method for determining the risk of preeclampsia”; WO2018051125A1)." (PMID 32617576, 2021). "In this study, we demonstrate in the RUPP model of preeclampsia, the presence of diastolic dysfunction and cardiac fibrosis in association with increased cardiac FKBPL levels." (PMID 33879252, 2021). "Our results show that the CD44/FKBPL ratio is associated with the risk of preeclampsia independently of established risk factors including age, BMI, MAP, and weight gain, from 20 weeks of gestation." (PMID 32617576, 2021). "This approach highlights the novelty of our microfilter-based delivery system in advancing placental research and addressing reproductive disorders, as well as the therapeutic potential of MSC-sEVs and FKBPL-relevant mechanisms for managing preeclampsia-associated dysfunction." (PMID 41285723, 2025). "We demonstrated that FKBPL expression analyzed against its target, CD44, as a CD44/FKBPL ratio, could be used as a potential predictive and diagnostic tool for preeclampsia, although its role in the pathogenesis of preeclampsia requires further elucidation." (PMID 36652019, 2023). "We next used our placenta-on-a-chip model to assess the invasive and migratory ability, as well as regulation of FKBPL and Gal-3, under inflammatory conditions (a hallmark feature of preeclampsia), of trophoblasts in the absence and presence of endothelial cells." (PMID 36652019, 2023). "The plasma CD44/FKBPL ratio could provide a novel risk stratification approach for preeclampsia at 20 weeks of gestation, capable of identifying women at high risk, who otherwise appear healthy." (PMID 32617576, 2021). "At 20 weeks of gestation, the CD44/FKBPL ratio in combination with mean arterial blood pressure (MAP) was capable of predicting a four-fold increased risk of preeclampsia in nulliparous pregnant women; most of the pregnancies in our cohort proceeded to develop late-onset preeclampsia." (PMID 32617576, 2021).
preeclampsia (continued). "Furthermore, recent data have demonstrated that FKBPL could be used as a diagnostic and/or treatment target for cardiovascular diseases (CVDs), placental health and preeclampsia." (PMID 36652019, 2023). "FK506-binding protein-like (FKBPL) has been identified as a potential biomarker as it is significantly downregulated in early pregnancy stages of women who progress to develop preeclampsia." (PMID 41285723, 2025). "In comparison to the control group, patients with early-onset preeclampsia displayed a significantly elevated plasma FKBPL signal (approximately 20%), while preeclampsia samples demonstrated a significant decrease in CD44 signal strength (around 40%)." (PMID 39744682, 2025). "In women before or with preeclampsia, FKBPL plasma concentration was initially significantly reduced but later significantly increased, respectively, suggesting a complex role in the disease." (PMID 41285723, 2025). "Given that metformin and aspirin have already been tested for the treatment or prevention of preeclampsia in humans, respectively, we also wanted to explore novel treatments including FKBPL-based peptide mimetic, AD-01." (PMID 40109359, 2025). "Using these models, we tested a number of clinically available and novel therapeutics for preeclampsia including aspirin, metformin, resveratrol and FKBPL-based therapeutic peptide mimetic, AD-01." (PMID 40109359, 2025). "It was determined that FKBPL and Gal-3 are present in increased concentrations in preeclampsia positive samples." (PMID 41050941, 2024). "Placental FKBPL protein expression was over two-fold higher from women with preeclampsia compared to normotensive controls (control 1.00 ± 0.22 vs preeclampsia 2.28 ± 1.99, fold change, p = 0.02)." (PMID 36652019, 2023). "Here, we confirmed that following diagnosis of preeclampsia, FKBPL expression was significantly increased in the plasma and placentae of our new validation group of women with preeclampsia compared to normotensive controls." (PMID 36652019, 2023). "We recently showed that plasma and placental FKBPL expression levels were significantly higher in a cohort of pregnant women with preeclampsia compared to normotensive pregnancies." (PMID 36652019, 2023). "Plasma samples analysed by ELISA demonstrated a significant increase in FKBPL concentration in women with preeclampsia compared to normotensive pregnancies (control 0.88 ± 0.35 vs preeclampsia 1.41 ± 0.42, ng/mL, p < 0.0001)." (PMID 36652019, 2023). "In a separate study using human plasma samples, high systemic FKBPL levels were reported in people with cardiovascular disease including diastolic dysfunction and established preeclampsia." (PMID 36302992, 2023). "In preeclampsia, FKBPL and its target protein, CD44, have demonstrated their predictive and diagnostic biomarker potential, likely reflective of the pathogenesis of preeclampsia and placental hypoxia." (PMID 34149611, 2021). "A novel anti-angiogenic protein, FK506-binding protein like (FKBPL), has recently been identified as having predictive and diagnostic roles in preeclampsia as well as being a determinant of CVD." (PMID 33879252, 2021). "Human samples prediagnosis (15 and 20 weeks of gestation; n ≥ 57), or postdiagnosis (n = 18 for plasma; n = 4 for placenta) of preeclampsia were used to determine FKBPL and CD44 levels, compared to healthy controls." (PMID 32617576, 2021). "Statistical significance was maintained (P = 0.02) when the CD44/FKBPL ratio was adjusted for differences in gestational age between the preeclampsia and control groups, using logistic regression." (PMID 32617576, 2021). "The effects of plasma secretome collected from women with preeclampsia on FKBPL expression levels were evaluated in in vitro 3D cardiac spheroid model to determine its potential role in the human heart." (PMID 33879252, 2021).